TLR4 (toll like receptor 4)
Diseases named in the same sentence as TLR4 in open-access papers (continued):
Sharing a sentence is not in itself a finding about the gene and the disease.
Insulin resistance (continued). "Also, our results disagree with an animal study that described that lncRNA MEG3 aggravates chronic inflammation and insulin resistance in adipocytes by stimulating TLR4/NF-KB while its downregulation had the reverse actions." (PMID 38985298, 2024). "Indeed, although a specific resistin receptor has not yet been identified, TLR4 has been recognized as a binding site for resistin, where it activates a TLR4-mediated signaling pathway involved in resistin-induced inflammation and insulin resistance." (PMID 39558137, 2024). "Both the TLR4 pathway and downstream mitochondrial alterations could therefore be of potential interest in the development of pharmacological treatments against insulin resistance." (PMID 37435031, 2023). "Through the use in vivo and vitro mice models, it is confirmed that saturated FAs stimulate toll-like receptor 4 (TLR-4), activating sphingomyelinase (SMase) and converting sphingomyelins to ceramide, which reduces sphingomyelins content and exerts an action of insulin resistance." (PMID 36837846, 2023). "TLR4 inhibition mitigated sEV-mediated liver inflammation and hepatocyte insulin resistance." (PMID 37896221, 2023). "It is possible that other TLR4-expressing cells in Tlr4LKO mice could influence insulin signaling molecules and contribute to alcohol-induced insulin resistance." (PMID 36979389, 2023). "Also, during bed rest, several organs produce more nuclear factor kappa-light-chain-enhancer of activated B cells (NF-B) and toll-like receptor 4 (TLR4), and these inflammatory markers are linked to insulin resistance and hyperglycemia." (PMID 37187644, 2023). "We hypothesized in this study that in human SkM, mitochondrial morphology could be regulated by the TLR4 pathway, which could in turn contribute to changes in insulin resistance." (PMID 37435031, 2023). "Hence, targeting the TLR4/NF-κB or TLR4/JNK will inhibit inflammatory responses in adipose tissue and associated insulin resistance in obese patients." (PMID 37626701, 2023). "Moreover, innate Toll-like receptor 4 (TLR4) is a key player in the inflammation induced by insulin resistance (IR) in the liver, linking it to the broader spectrum of liver inflammation." (PMID 38090595, 2023). "Like eritoran, the effects of TAK-242 have been studied primarily with i.v. administration; whether this or other TLR4 antagonists could be administered orally for chronic treatment of insulin resistance remains undetermined." (PMID 36066991, 2022). "It is also possible that other TLR4 inhibitors with a different mechanism of action may be more effective against insulin resistance." (PMID 36066991, 2022). "Thus, in this study, we used a TLR4 inhibitor to directly examine the role of TLR4 on insulin resistance in humans." (PMID 36066991, 2022). "Moreover, celastrol reverses palmitic acid-induced insulin resistance by activating Toll-like receptor (TLR4)/myeloid differentiation factor 2 (MD2)/NF-κB signalling." (PMID 36009315, 2022). "Interestingly, it was found that TLR4 mediates lipid-induced insulin resistance, providing another link among membrane aging, inflammation, IKKB/NF-kB activation, and insulin resistance." (PMID 36274849, 2022). "Moreover, palmitic acid can also induce insulin resistance of macrophages in vitro by upregulating galectin-3 (Gal-3) expression and promoting the TLR4/phosphorylated-NF-B signaling pathway." (PMID 36355546, 2022). "In addition, a recent study reported that WISP1 contributes to obesity-induced liver steatosis and skeletal muscle insulin resistance via TLR4-mediated NF-κB- and JNK-dependent pathways 73, 74)." (PMID 35909571, 2022). "Interestingly, it has also been reported that the administration of bile acids inhibits the TLR4-NF-κB signaling pathway, and thereby reduces inflammation and insulin resistance." (PMID 36532435, 2022).
Insulin resistance (continued). "Future studies with TLR4 inhibitors with different pharmacodynamic and pharmacokinetic properties may help to further clarify the role of TLR4 in insulin resistance in humans." (PMID 36066991, 2022). "In addition, TLR4 can mediate hyperglycemia, insulin resistance and proinflammatory molecule production, decreasing ApoM gene expression and plasma ApoM, damage gut-vascular barrier (GVB), thereby aggravate the intestinal function." (PMID 36088483, 2022). "We tested the hypothesis that pharmacologic blockade of TLR4 with the competitive inhibitor eritoran would improve insulin resistance in humans." (PMID 36066991, 2022). "Furthermore, Fetuin-A serves as an endogenous ligand for toll-like receptor 4, mediating free fatty acid-inflicted TLR4 signaling activation to induce insulin resistance." (PMID 34944728, 2021). "The TLR4 also involves insulin resistance (IR) and inflammation developments." (PMID 33996978, 2021). "Beside, resistin, an adipokine, also promotes inflammation and insulin resistance via TLR4." (PMID 33686181, 2021). "TLR4 has been reported to selectively increase sphingolipid levels within the cell, suggesting that ceramides may be an important mediator of insulin resistance induced by TLR4 signalling." (PMID 34580412, 2021). "In addition to insulin resistance, fetuin-A can also promote lipotoxicity in β cells through the TLR4-JNK-NF-kB signaling pathway." (PMID 33807959, 2021). "TLR4 KO mice are protected from lipid treatment- or HFD-induced insulin resistance." (PMID 33498410, 2021). "In contrast, TLR4 knockout mice oppose the HFD-induced insulin resistance, and atherosclerosis." (PMID 35052763, 2021). "In particular, palmitic acid that could lead to insulin resistance by binding directly with MD2 to activate TLR4/NF-κB signal pathway." (PMID 33849559, 2021). "TLR4 knockout mice were protected from high-fat diet-induced insulin resistance." (PMID 34832960, 2021). "Moreover, restoring PRSS8 hepatic synthesis of the LKO mice decreased TLR4 expression and ameliorated insulin resistance with the HFD." (PMID 34361079, 2021). "Moreover, inflammation and insulin resistance can prevent by distorted expression of TLR4, in response to severe variations in dietary fat." (PMID 33924088, 2021). "TLR4 is a widely known mediator of inflammatory response in adipose tissue, skeletal muscle, islets, and liver, thereby at least in the last case contributing to insulin resistance." (PMID 34361079, 2021). "Our experiments indicated that NEFAs could activate the NF-κB inflammatory signaling pathway and influence insulin resistance through TLR4." (PMID 34966805, 2021). "UFAs are deemed as activators of the innate immune component Toll-like receptor 4 (TLR4) and this modulatory effect may be associated with the function of Dop in alleviating insulin resistance." (PMID 35155528, 2021). "Toll-like receptor 4 (TLR4) is known to contribute to insulin resistance and obesity." (PMID 32576879, 2020). "The overexpression of muscle TLR4 has been described in subjects with insulin resistance." (PMID 32708841, 2020). "Conversely, TLR-4 over-expression leads to a certain degree of adipose insulin resistance." (PMID 33028294, 2020). "“Metabolic endotoxemia” may promote inflammatory reactions and insulin resistance in HFD-fed rats through TLR4 signaling." (PMID 32024509, 2020). "Metabolic stress induces activation of TLR4 signaling in immune cells, leading to release of proinflammatory cytokines for recruitment of macrophages to adipose tissue, potentially exacerbating chronic inflammation and insulin resistance." (PMID 33376487, 2020). "Similarly, TLR4 mediates ceramide-mediated insulin resistance and inhibition of TLR4 eliminates oxidative stress induced by palmitic acid in endothelial cells." (PMID 32947825, 2020).
Insulin resistance (continued). "Therefore, TLR4 and AP1 potentially provide targets for therapeutic intervention to improve hepatic insulin resistance and lipid deposition caused by nutrient excess and lipid overload." (PMID 33013197, 2020). "Interestingly, Cer synthesis is a requisite for the TLR4-induced insulin resistance and the activation of TLR4 is able to induce insulin resistance in certain brain regions (i.e., the hypothalamus)." (PMID 31001082, 2019). "Similarly, to LPS, palmitate can initiate signals through TLR4 and activate NF-κβ, MAPKs, and AP-1, which are known to play a role in inflammation and insulin resistance." (PMID 31443599, 2019). "Interestingly, intracerebroventricular (ICV) resistin treatment induces overall inflammation and insulin resistance through the activation of hypothalamic TLR4 signaling pathway." (PMID 30845245, 2019). "Eritoran (E5564), an antagonist of TLR4, has been terminated under clinical trials in patients with insulin resistance and T2DM for unknown reasons (NCT02321111 and NCT02267317)." (PMID 31582899, 2019). "Inflammation and LPS-induced insulin resistance were improved when TLR4 was inhibited." (PMID 30897784, 2019). "TLR4 signaling involves docking with several intracellular proteins, among these is myeloid differentiation factor 88 (MyD88), which appears to potentiate the intracellular signaling of TLR4-induced insulin resistance." (PMID 31263701, 2019). "In addition, hematopoietic knockout of TLR4 in obese mice demonstrated a crucial role of TLR4 in inducing insulin resistance in liver and adipose tissue, especially in KCs and macrophages." (PMID 30405618, 2018). "Importantly, alteration of gut microbiota or intestinal permeability, as observed in insulin resistance-related conditions, has been shown to increase gut-derived LPS circulating levels, thus resulting in systemic activation of TLR4-driven immune response." (PMID 30206293, 2018). "Additionally, FFA triggers insulin resistance by direct activation of Toll-like Receptor 4 (TLR4) and the innate immune response." (PMID 30170598, 2018). "The same mechanism of stimulation of TLR-4 signaling via NEFAs was observed in insulin resistance." (PMID 30235348, 2018). "Thus, increased TLR4-driven signalling in muscle from insulin-resistant obese and/or type 2 diabetic subjects contributes to worsening insulin-resistance and inflammation." (PMID 28240307, 2017). "Our results demonstrate that ARC-restricted TLR4 knockdown protects obese rats from diet-induced weight gain and energy intake, from diet-induced impaired glucose homeostasis and peripheral insulin resistance, and from high-fat diet-induced hepatic steatosis and adipocyte hypertrophy." (PMID 28785099, 2017). "Endotoxin-driven TLR4 signaling is thought to be related to insulin resistance." (PMID 28349245, 2017). "Tlr4 expression is increased in adipose tissues, peripheral blood or muscle of obese or type 2 diabetes patients and in adipose tissues of obese db/db mice and correlates with insulin resistance." (PMID 29163467, 2017). "We generated two transgenic (TG) mouse lines expressing a constitutively active TLR4 in adipose tissue and determined whether these TG mice would show increased insulin resistance." (PMID 28776958, 2017). "It is confirmed that deletion of TLR-4 can prevent the high-fat diet-induced insulin resistance." (PMID 27429803, 2016). "Deletion of TLR-4 prevents the HFD–induced insulin resistance." (PMID 27105827, 2016). "Both TLR4- and TLR9-deficient mice are protected from high-fat diet-induced inflammation and insulin resistance, while mice deficient in TLR5 develop all features of metabolic syndrome including hyperphagia, obesity, insulin resistance, pancreatic inflammation, and hepatic steatosis." (PMID 27247565, 2016). "It is crucial to note that HMGB-1 may induce islet cells apoptosis and insulin resistance via binding to TLR4 and then contribute to initiation and development of DM." (PMID 27847406, 2016).
Insulin resistance (continued). "This happens via receptors that bind to advanced glycation end products, such as RAGE (advanced glycosylation end product-specific receptor), TLR4 and other receptors that regulate the activity of NFκB, constituting another link between diet and insulin resistance." (PMID 27437032, 2016). "Similarly, the development of insulin resistance by LPS binding to TLR4 leads to the secretion of inflammatory cytokines that induce a state of insulin resistance." (PMID 27445441, 2016). "Inhibition of Tlr4 suppressed this inflammatory response and resolved the insulin resistance." (PMID 27617199, 2016). "We hypothesized that pharmacological TLR4 inhibition would protect against hepatic and peripheral insulin resistance in rats challenged with lipid infusion or high fat feeding." (PMID 26196892, 2015). "TLR4-mutant mice were partially protected against long-term HFD-induced insulin resistance." (PMID 26539824, 2015). "In this regard, pharmacological inhibitors of TLR4 might be useful therapeutics in the treatment of insulin resistance and T2DM." (PMID 26196892, 2015). "In the present study, we hypothesized that TLR4 signaling mediates both peripheral and cardiac insulin resistance." (PMID 26539824, 2015). "Additionally, TLR4-mutant mice were partially protected against these metabolic disorders, suggesting that activation of TLR4 contributes to HFD-induced peripheral insulin resistance." (PMID 26539824, 2015). "TLR4 induced large amounts of cytokine release, which is also observed in insulin resistance." (PMID 26576220, 2015). "In addition, TLR4 expression is primarily upregulated in visceral adipose tissue during insulin resistance." (PMID 26539824, 2015). "Although TAK-242 and E5564 were ineffective in significantly reducing mortality in severely septic patients, TLR4 inhibitors may be beneficial for low-grade inflammatory diseases characterized by insulin resistance." (PMID 26196892, 2015). "Knockdown of TLR4 by siRNA in HFD mouse livers significantly improved their insulin resistance." (PMID 24614850, 2014). "Damage-associated molecular pattern molecules may also interact with TLR4, i.e. oxidized low-density lipoprotein (LDL), one of the atherogenic lipoproteins associated with atherosclerosis and insulin resistance." (PMID 25360682, 2014). "Similarly, macrophages also play an important role in insulin resistance and β-cell dysfunction through fatty acid-induced TLR4 activation." (PMID 24357461, 2014). "Knockdown of myeloid differentiation primary response gene 88 (MYD88), an adaptor protein for TLR4, improved the insulin resistance in LKO mice, and overexpression of PRSS8 in the liver did not decrease blood glucose levels during the GTT and PTT in systemic TLR4 KO mice." (PMID 24614850, 2014). "Deletion of TLR-4 prevented the high-fat diet–induced insulin resistance." (PMID 25030027, 2014). "Thus, FFA-Fetuin-A induced TLR4 activation is very important in the lipid-induced inflammation and insulin resistance and type 2 diabetes." (PMID 24143207, 2013). "Moreover, disrupted expression of TLR4 protects mice from developing inflammation and insulin resistance in response to chronic changes in dietary fat." (PMID 23704966, 2013). "Another support for our model comes from a recently reported functional study in which the alpha-2-HS-glycoprotein (ASHG) has been identified as an adaptor protein that links saturated fatty acids to toll-like receptor 4 thus stimulating inflammatory pathways leading to insulin resistance." (PMID 23308243, 2013). "Taken together, these findings suggest that elevations in plasma LPS concentration found in obese and T2DM subjects could play a role in the pathogenesis of insulin resistance and that antagonists of TLR4 may improve insulin action in these individuals." (PMID 23704966, 2013).
Insulin resistance (continued). "For instance, lipid infusion caused the accumulation of macrophages in adipose tissue accompanied by insulin resistance in WT control mice, but this was not the case in TLR4-deficient mice." (PMID 23964268, 2013). "Thus, while the role of Tlr-4 during early development of muscle insulin resistance warrants further investigation it is clear that inflammation in muscle plays a minimal role in the development of early muscle insulin resistance." (PMID 23951235, 2013). "The function of TLR4 is to mediate trans-membrane signaling transduction in which TLR4 could serve as a bridge that links innate immunity, lipid metabolism, insulin resistance, and vascular inflammation." (PMID 23251812, 2012). "This investigation tests the hypothesis that expressions of TLR2 or TLR4 on monocytes and related inflammatory cytokines, such as TNF-α and IL-6, might be associated with insulin resistance in patients with RA." (PMID 23213270, 2012). "Toll-like receptor 4 (TLR4) could serve as a bridge that links innate immunity, lipid metabolism, and insulin resistance." (PMID 23251812, 2012). "Differential effects of saturated and n-3 fatty acids on TLR-4 signaling may explain the variation in insulin resistance." (PMID 21388548, 2011). "TLR4 contributes to the development of insulin resistance and inflammation through its activation by elevated exogenous ligands (e.g., dietary fatty acids and enteric lipopolysaccharide) and endogenous ligands (e.g., free fatty acids) which are elevated in obese states." (PMID 20814545, 2010). "Genetic studies with replications in non-diabetic individuals in regard to their fat distribution or insulin resistance according to their carrier status of a common toll-like receptor 4 (TLR4) variant (TLR4D299G/T399I) are still lacking." (PMID 21125016, 2010). "For the purposes of this review, we will focus on the role of TLR4 in insulin resistance." (PMID 20814545, 2010). "However, the specific hepatokine(s) that mediate hepatocyte TLR4-induced inflammation and insulin resistance following chronic alcohol feeding are largely unknown and require further investigation." (PMID 36979389, 2023). "However, it is largely unknown whether hepatocyte TLR4 contributes to the development of insulin resistance induced by chronic alcohol drinking." (PMID 36979389, 2023). "Moreover, other work suggests that TLR4 may not function as a receptor for saturated FAs and that fetuin-A acts as a TLR4 endogenous ligand that mediates lipid-induced insulin resistance." (PMID 36066991, 2022). "Likewise, the activation of TLR4 induces insulin resistance in adipocytes." (PMID 33498410, 2021). "However, no studies on the relationship between NEFAs, TLR4/NF-κB and the insulin resistance signaling pathway, nor how NEFAs cause insulin resistance in primary calf hepatocytes, have been carried out." (PMID 34966805, 2021). "Moreover, TLR2 and TLR4 activity was markedly increased in association with elevated TNF-α, IL-6, and IFN-γ expressions, increased insulin resistance in response to inflammation; the changes were more prominent in diabetic patients with end-stage renal disease and renal failure." (PMID 33442388, 2020). "TLR4 signaling pathways can induce the production of proinflammatory cytokines by modulating the activity of NF-κB, and the enhanced activation of NF-κB pathways may induce insulin resistance via the dephosphorylation of Akt and GSK-3β." (PMID 32685087, 2020). "Particularly, LPS could activate TLR4-induced insulin resistance." (PMID 33281537, 2020). "The activation of TLR4 may contribute to MeS, insulin resistance and endoplasmic reticulum stress." (PMID 32708841, 2020). "All together, these data clearly reveal resistin/TLR4 as a new regulatory pathway of neuronal autophagy, and suggest that resistin-dependent neuronal autophagy could be a key contributor of hypothalamic inflammation and insulin resistance." (PMID 30906281, 2019).